IL6R (interleukin 6 receptor)
Diseases named in the same sentence as IL6R in open-access papers (continued):
Sharing a sentence is not in itself a finding about the gene and the disease.
breast carcinoma (continued). "ADM-resistant breast cancer cell lines also expressed more IL-6 and IL-6R than Adriamycin (ADM)-sensitive cell lines." (PMID 28388577, 2017). "IL-6 and its downstream signal network (IL-6/IL-6R/gp130) are reported to play important roles in breast cancer." (PMID 27231908, 2016). "After activated by IL-6 derived from metastasizing breast cancer cells, MDSCs can express both IL-6 and soluble IL-6Rα, which stimulate STAT3 phosphorylation through IL-6 trans-signaling in breast cancer cells." (PMID 27542274, 2016). "Previous research also indicated that increased resistance to apoptosis in human breast cancer was induced by high expression of IL-6 and IL-6R." (PMID 26313265, 2015). "The idea that YB-1 is a transcription factor that activates IL-6 promoter activity is in agreement with a ChIP sequencing study in trastuzumab-resistant breast cancer cells that identified IL-6 and IL-6R as YB-1 transcriptional targets." (PMID 26512918, 2015). "What is more, the dysregulated genes IL2RG, IL6R, IL7R and TGFB2 have been reported to be associated with metastasis site or prognosis, and CCR6 is associated with both live metastasis in breast cancer and bone metastasis in human neuroblastoma." (PMID 25163697, 2014). "Interestingly, there are reports that bronchial epithelial cells can express IL-6, and that IL-6 can act as a paracrine growth in breast cancer cell lines, which can upregulate both the soluble IL-6R and membrane bound IL-6R." (PMID 41497628, 2025). "Blocking IL6R using an IL6R antibody reversed IL6-induced breast cancer metastasis." (PMID 40841364, 2025). "Furthermore, breast cancer patients with a combined high tGAS+IL-6/IL-6R/GP130 activation had worse MFS when compared to patients with low tGAS+IL-6/IL-6R/GP130 activation." (PMID 39768178, 2024). "Therefore, enhancements of MCT-1, IL-6/IL-6R, CXCL7 and PD-L1 expression are risk factors for predicting breast cancer violence and unfavorable clinical outcomes." (PMID 38505617, 2024). "Significantly, our analysis of 620 breast cancer patients treated with anthracyclines or taxanes showed that patients with primary tumors expressing high levels of IL-6R or CCR2 are significantly less likely to respond to either chemotherapy compared with low receptor expression." (PMID 37607007, 2023). "Furthermore, elevated mRNA level of ADAM19, which can cleave IL6-Rα, was found in breast cancer patient T cells." (PMID 37741983, 2023). "Furthermore, it has been shown that high expression of IL-6Rα induces resistance to apoptosis in breast cancer." (PMID 36835413, 2023). "High expression of IL-6Rα was also demonstrated to induce apoptosis resistance in breast cancer." (PMID 35924148, 2022). "In addition, the increased expression of IL-6R correlated with disease progression and poor patient outcome in breast cancer." (PMID 35406622, 2022). "Our data suggest that miR-23c may interfere with IL-6R/STAT3 signaling in breast cancer cell lines and that the upregulation of miR-23c in these cells reduces cell proliferation and migration by inhibiting IL-6R/STAT3 signaling." (PMID 35406622, 2022). "Among miRNAs potentially involved in the cross-talk between EGFR-stimulated MSCs and breast cancer cells, we identified miR-23c and suggested a role of this miRNA as a tumor suppressor in MDA-MB-468 and MDA-MB-231 breast cancer cells, through the inhibition of IL-6R." (PMID 35406622, 2022). "This review covers the current biological understanding of the IL-6 signaling pathway and its impact on breast cancer metastasis, as well as, therapeutic interventions that target components of the IL-6 pathway including: IL-6, IL-6Rα, gp130 receptor, JAKs, and STAT3." (PMID 35371975, 2022). "Agents directly targeting the IL-6/IL-6R/gp130 complex for breast cancer therapy." (PMID 35924148, 2022).
breast carcinoma (continued). "Moreover, MCTS1 has been shown to exert oncogenic effects on breast cancer progression by affecting multiple cancer-related signaling pathways, including modulation of c-Myc translation, IL-6/IL-6R signaling pathway, and Src/p190B signaling pathway." (PMID 35295953, 2022). "We hypothesized that BQ overexpression might enhance the expression of IL-6R in breast cancer and was able to confirm that BQ overexpression could indeed enhance the expression of IL-6R in breast cancer cells at both mRNA and protein levels." (PMID 33806019, 2021). "Through in vivo study, we confirmed the clinical significance of IL-6R in breast cancer." (PMID 33806019, 2021). "However, the methylation status of some IL6R CG probesets represented a favorable prognostic factor in breast cancer, glioblastoma, lower grade glioma, melanoma, and thymoma." (PMID 34576335, 2021). "Similarly, an alternative approach to target cancer angiogenesis using an siRNA-based silencing approach was reported by Bharti and colleagues, who focused on IL-6/IL-6R and mitochondrial signaling in breast cancer." (PMID 33322132, 2020). "Breast cancer cell-derived IL-6 promotes IL-6 and IL6Rα expression in MDSCs, and IL-6 trans-signaling in cancer cells activates STAT phosphorylation, thereby promoting breast cancer invasion and metastasis in a mouse model established through a xenograft of human breast cancer cells." (PMID 32726950, 2020). "Inhibition of IL-6/IL-6R with Dia displayed the similar effect in hypoxic breast cancer cells." (PMID 29695771, 2018). "With an increased understanding of the IL-6/IL-6R/gp130 regulatory axis and signaling in breast cancer, it may be possible to design new IL-6 therapies which will be more effective." (PMID 26840088, 2016). "However, preclinical and clinical studies of the applications of anti–IL-6/IL-6R/gp130 therapy in breast cancers are limited." (PMID 26840088, 2016). "In this review, we summarize the structures, preclinical and clinical studies, mechanisms of action of chemical and biological blockers that directly bind to IL-6, IL-6R, or gp130, and the potential clinical applications of these pharmacological agents as breast cancer therapies." (PMID 26840088, 2016). "IL-6 appears to play a critical role in the growth and metastasis of breast cancer cells, renewal of breast cancer stem cells (BCSCs), and drug resistance of BCSCs, making anti–IL-6/IL-6R/gp130 therapies promising options for the treatment and prevention of breast cancers." (PMID 26840088, 2016). "The functional importance of IL6-STAT3 activation in PTEN-deleted HER2-positive breast cancer was demonstrated in a study showing that the IL6R antibody, alone or in combination with trastuzumab, decreased the cancer stem cell population and inhibited development of distant metastasis." (PMID 26234940, 2015). "Furthermore, tGLI1 and IL-6/IL-6R/GP130 were significantly co-activated in HER2-enriched breast cancer and TNBC when compared to luminal patients, as validated by two separate breast cancer datasets, The Cancer Genome Atlas (TCGA) and the Gene Expression Omnibus (GEO)." (PMID 39768178, 2024). "The KM survival curves showed that CD46, JAG1, IL6, and IL6R were all risk factors that lead to poor prognosis in breast cancer patients, which implies that the enhanced interaction between CD46-JAG1 leads to poor prognosis in breast cancer patients, along with the IL6-(IL6R+IL6ST) axis." (PMID 38571938, 2024). "Due to the clinical evidence that co-activation of the tGLI1 and IL-6/IL-6R/GP130 signaling pathways is associated with more aggressive subtypes in breast cancer patients, we next examined the role of tGLI1 and GP130 in the HER2-enriched breast cancer and TNBC stem cell subpopulation in vitro." (PMID 39768178, 2024).
breast carcinoma (continued). "The blockade of IL-6 would serve to block the downstream, protumourigenic effects of TAMs, thus supporting the idea that targeting of IL-6R and gp130 may present a better approach to inhibition of this pathway in breast cancers instead of the use of JAK/STAT3 inhibitors." (PMID 35053592, 2022). "Thus, our study not only confirms that IL-6R could be an independent prognostic factor in ER+ breast cancer, but could also be a possible target to suppress tamoxifen resistance." (PMID 33806019, 2021). "Moreover, we found a strong correlation between interleukin-6 receptor gene expression and inflammation, mitochondrial functionality, and oxidative stress markers, as well as with estrogen receptor beta, in breast cancer human samples in different BMI situations." (PMID 34573003, 2021). "However, the studies of IL-6/IL-6R/gp130 immunotherapy for treatment of breast cancers are limited." (PMID 30885232, 2019). "IL-6R Ab might be a more promising therapeutic strategy for breast cancer." (PMID 30083161, 2018). "Therefore, combination therapy with ER antagonists and IL-6/IL-6R/gp130 inhibitors may provide a novel therapeutic strategy for ER+ breast cancers." (PMID 26840088, 2016). "Together, these findings support the preclinical development of huE17 and huNA7 and the potential of dual IL-6R and GP130 targeting in IL-6-driven breast cancer." (PMID 42316398, 2026). "We examined S100A8, IL-6, IL-6R, IL-8, and CXCL3 genes; each of these are known to be differentially expressed in breast cancer and are being evaluated as biomarkers and therapeutic targets." (PMID 39199680, 2024). "Breast cancer tumorspheres presented a statistically significant increase in CXCL8, IL6, IL6R, and NFKB1 mRNA levels in comparison to adherent cell culture, while TGFB1 mRNA expression was decreased." (PMID 39336151, 2024). "In this study, we identified tGLI1 and IL-6/IL-6R/GP130 signaling pathways to be frequently co-overexpressed, co-activated, and functionally cooperate to promote breast CSCs in HER2-enriched breast cancer and TNBC." (PMID 39768178, 2024). "To date, two IL-6Rα monoclonal antibodies (mAbs), a JAK1/2 inhibitor, and a small-molecule STAT3 inhibitor are being clinically investigated for breast cancer." (PMID 39768178, 2024). "tGLI1+IL-6/IL-6R/GP130 signaling is frequently co-enriched and co-activated in HER2-enriched breast cancer and TNBC when compared to luminal subtypes." (PMID 39768178, 2024). "successfully developed liposomes that carry anti‐CD44 antibodies and anti‐IL6R antibodies that specifically target the TME of CD44+ breast cancer cells, thereby inhibiting metastasis in breast cancer mouse models." (PMID 37560754, 2023). "Transcriptomic data from TEPA treated breast cancer cells also displays changes in the immune-related genes (including IL6, IL6R, IL15, CXCL1, CXCL8, and PTX3) in breast cancer." (PMID 37480151, 2023). "The data illustrating that IL-6, IL-8 and the receptors sortilin, IL-6R and IL-6-ST were highly secreted from PDS-adapted breast cancer cell lines support the fact that the PDS model includes a microenvironment promoting the cancer stem cell population." (PMID 38136303, 2023). "The IL-6 signal transduction pathway including IL-6, IL-6R, sIL-6R, gp130, JAK, and STAT3 has been suggested as promising therapeutic targets for breast cancer." (PMID 35924148, 2022). "IL-6R is involved in the IL-6/IL-6R/STAT3 signaling pathway, whose role in breast cancer progression has been extensively demonstrated." (PMID 35406622, 2022). "This study identifies the molecular mechanisms through which BQ323636.1 can enhance IL-6 and IL-6R expression, which leads to the activation of STAT3 and the development of tamoxifen resistance in ER+ breast cancer." (PMID 33806019, 2021). "Our study has elucidated the molecular mechanism through which BQ can modulate the expression of IL-6 and IL-6R and thus the activation of STAT3 in breast cancer." (PMID 33806019, 2021).
breast carcinoma (continued). "Tocilizumab, as an FDA-approved humanized monoclonal antibody against IL-6R, has been proposed to inhibit the trastuzumab-resistant HER2(+) breast cancer." (PMID 32653013, 2020). "In fact, only one trial evaluated the dose-limiting toxicity of the anti-IL-6R monoclonal antibody tocilizumab in combination with trastuzumab and pertuzumab in subjects with metastatic HER2-positive breast cancer." (PMID 31847214, 2019). "Further analysis of the breast cancer cDNA arrays (n = 124) confirmed positive correlations of MCT-1 expression with that of IL-6 (r = 0.48, p < 0.001) and IL-6R (r = 0.27, p = 0.002)." (PMID 30885232, 2019). "Presence of excess IL-6R, as well as significant low MAO-A were observed in high grade IDC of breast cancer." (PMID 29695771, 2018). "IL-6R Ab and a specific STAT3 antagonist inhibited the growth and metastasis of IL-6+ mammary cancer in vivo and dramatically reduced the accumulation of e-MDSCs." (PMID 30083161, 2018). "Previous studies of breast cancer indicated that MDSCs express ADAM-family proteases and IL-6Rα, which contribute to breast cancer cell invasiveness and distant metastasis through the IL-6 trans-signaling pathway in murine models." (PMID 29326716, 2017). "We have previously shown that Syndecan-1 modulates the expression of IL-6, IL-6R in different experimental models of inflammation and in MDA-MB-231 breast cancer cells." (PMID 28270211, 2017). "In this study, we exploit two signaling pathways frequently hyperactivated in breast cancer, truncated glioma-associated oncogene homolog 1 (tGLI1) and interleukin-6/interleukin-6 receptor/glycoprotein 130 (IL-6/IL-6R/GP130) signaling, to directly target HER2-enriched breast cancer and TNBC." (PMID 39768178, 2024). "Interestingly, BZA exhibited preclinical efficacy against HR-breast cancer, which was later attributed to its ability to bind the D1 domain of the GP130 receptor and subsequently disrupt IL-6/IL-6R/GP130 signaling." (PMID 39768178, 2024). "High tGAS+IL-6/IL-6R/GP130 activation did not significantly impact MFS in luminal breast cancer patients when compared to low tGAS+IL-6/IL-6R/GP130." (PMID 39768178, 2024). "The expression values for tumour cytoplasmic IL6R were not significantly different across the molecular subtypes of breast cancer (p = 0.230)." (PMID 37199043, 2023). "The expression values for tumour membrane IL6R were not significantly different across the molecular subtypes of breast cancer (p = 0.714)." (PMID 37199043, 2023). "We have successfully illustrated that targeting IL-6R could be an alternative way to suppress IL-6/STAT3 pathway in breast cancer and demonstrate the usage of TCZ could reduce tamoxifen resistance in breast cancer." (PMID 33806019, 2021). "In the current study, we demonstrate that BQ overexpression could enhance the expression of IL-6 and IL-6R, which in turn activates the IL-6/STAT3 pathway to mediate tamoxifen resistance in breast cancer." (PMID 33806019, 2021). "IL-6/IL-6R antagonists as anti-breast cancer agents have not been broadly investigated and are even less studied in TNBC." (PMID 30885232, 2019). "Another report indicated that IL-6 and soluble IL-6R (sIL-6R) levels were increased after chemotherapy in breast cancer patients reporting CIPN as compared with those without CIPN." (PMID 31197114, 2019). "In addition, AKT3 was targeted by miR-29 in breast cancer, and cytokine receptor (IL2RB and IL6R) and one component of the PI3K complex (PIK3R3) were also targeted by miR-34a and miR-29, respectively, in DLBCL." (PMID 30820547, 2019). "Supporting this notion, the nanoparticles of anti- CD44 Ab encapsulating anti-IL-6R Ab target the TME and CD44+ BCSCs that inhibit the metastatic niche of triple-negative and luminal breast cancer in two mouse models, namely syngeneic BALB/c mice bearing 4 T1 cells and transgenic MMTV-PyMT mice." (PMID 30885232, 2019).
breast carcinoma (continued). "Thus, blocking of IL-6R in breast cancer cells and neutralization of secreted IL-6 decreased STAT3 activity in breast cancer cells." (PMID 29891854, 2018). "At present, the application of IL-6/IL-6R/gp130 blockers as anti-cancer agents has not been studied broadly, and to an even lesser extent for breast cancer." (PMID 26840088, 2016). "In basal-like and HER2-positive breast cancers, we demonstrated that a low WWOX/HIF1A ratio is particularly detrimental, as it triggers HIF1α-mediated upregulation of immunosuppressive mediators such as TLR4, NOTCH1, PTX3, and IL6R, alongside glycolytic enzymes like GLUT1 and HK2." (PMID 41007296, 2025). "TNBC cells expressing oncogenic multiple copies in T cell malignancy 1 (MCT-1) induces IL-6 via IL-6R and promotes macrophage polarization into M2-like macrophages while silencing MCT-1 and blocking IL-6R by tocilizumab, reducing IL-6R expression and macrophage polarization in breast cancer." (PMID 39858015, 2025). "Co-targeting of tGLI1 and IL-6R/GP130 has not been investigated in breast cancer or any tumor type." (PMID 39768178, 2024). "Collectively, our findings demonstrate that dual-targeting tGLI1 and IL-6/IL-6R/GP130 signaling pathways are effective against HER2-enriched breast cancer and TNBC and support the use of tGLI1 and IL-6/IL-6R/GP130 inhibitors for the treatment of these more aggressive subtypes of breast cancer." (PMID 39768178, 2024). "There are currently no FDA-approved IL-6/IL-6R/GP130 inhibitors for the treatment of breast cancer." (PMID 39768178, 2024). "However, IL-6 receptors IL-6Rα and gp130 were found to be reduced on naïve CD4+ T cells from breast cancer patients compared to healthy donors by flow cytometry, and expression levels correlated with signaling responsiveness to IL-6, identifying a potential mechanism of impaired signaling." (PMID 37741983, 2023). "On the whole, activation of JAK2-STAT3 and JAK2-STAT5 downstream of IL-6R and PRLR, respectively, may play a coordinated role in the development and progression of luminal breast cancer, suggesting the importance of these signaling cascades in ER-positive breast tumors." (PMID 37834225, 2023). "However, the application of IL-6/IL-6R blockers as anti-cancer agents has not been proved intensively in cancers including breast cancer." (PMID 35924148, 2022). "The authors showed how the inhibition of IL-6/IL-6R signaling by IL-6 siRNA suppressed angiogenesis/invasion by up-regulating MAO-A expression, a mitochondrial protein that commonly degrades monoamines and is usually found down-regulated in multiple cancers, including breast carcinoma." (PMID 33322132, 2020). "Since IL-6Rα and gp130 are required for signal transduction, the previous contradictory results may have been attributed to a lack of receptor expression in tested breast cancer cell lines, or that IL-6’s pleiotropic effects may depend on JAK/STAT3 pathway activation." (PMID 35371975, 2022). "The data show that all the breast cancer cell lines express varying levels of IL-6, CAP1 and IL-6R, whereas no expression of resistin is observed either at the protein or transcript level in any of the cell lines (data not shown)." (PMID 25868978, 2015). "Considering that the IL6/IL6R/GP130 signaling pathway is important in tumorigenesis and metastasis, bazedoxifene is thought to have an antitumor effect, which has been proven preliminarily in breast cancer and pancreatic cancer but has not yet been studied in non–small cell lung cancer (NSCLC)." (PMID 39152779, 2024).